PIWIL2 (piwi like RNA-mediated gene silencing 2)
Diseases named in the same sentence as PIWIL2 in open-access papers (continued):
Sharing a sentence is not in itself a finding about the gene and the disease.
Infertility (9 papers, 2012 to 2024). "Therefore, the homozygous frameshift deletion variant in PIWIL2 was suspected to be the causative variant of infertility in this patient." (PMID 36153567, 2022). "One might assert that PIWIL2 isoforms bearing various combinations of domains are bound to be of biological significance for such malconditions as infertility and tumors." (PMID 25384072, 2014). "To date, the association between PIWIL2 and infertility in humans has not yet been fully explained." (PMID 36153567, 2022). "In addition, gain of methylation in spermatogenesis-related gene promoters, including DAZL, PIWIl2 and TDRD1, is observed in spermatozoa and testicular samples from infertile human patients." (PMID 27880848, 2016). "We hypothesized that Piwil2 does not lead to terminal infertility; however, it affects the ovarian reserve via downregulated genes." (PMID 34639162, 2021). "The repression of PIWIL2 and TDRD1 gene expression in the severe spermatogenic defects examined in this study, leads us to speculate that the molecular alterations affecting piRNAs and their machinery are involved in human infertility." (PMID 23112866, 2012).
colon cancer (8 papers, 2010 to 2025). "The results from the SWAN and cBioportal analyses highlight the overall loss of regulation of the entire piRNA biogenesis pathway in colon cancer and identify PIWIL2 as a top candidate for the loss of the pathway's regulation." (PMID 40789164, 2025). "PIWIL2 is downregulated in colon tumors of advanced stage, nodal metastasis, and in certain subtypes, correlating with poor survival, while it is also downregulated in ulcerative colitis, an inflammatory bowel disease that predisposes to colon cancer." (PMID 40789164, 2025). "According to the cancer stem cells hypothesis, EIF2C1 and PIWIL2 proteins might play a role in the balance between colonic cancer stem cells self-renewal and division in association with small RNAs' pathway." (PMID 20146808, 2010). "Given that PIWIL2 exhibits the most allelic losses in the entire PIWI pathway and is also downregulated in ulcerative colitis and colon cancer correlating with disease progression, we sought to investigate whether loss of PIWIL2 may indeed promote pro-tumorigenic phenotypes." (PMID 40789164, 2025). "Furthermore, EIF2C1 and PIWIL2 might represent novel colon cancer markers with early diagnostic significance." (PMID 20146808, 2010). "Low PIWIL2 expression in colon tumors was also correlated with poor patient survival among all tumor stages, when stratified by stages 1-3 combined, and even more pronounced in stage 4, using the Kaplan–Meier Plotter web-based tool, which is in agreement with the CNA data." (PMID 40789164, 2025). "Shifted weighted annotation network (SWAN) analysis revealed that the pathway experiences significant allelic losses in colon cancer and that PIWIL2, the main catalytic component of the pathway responsible for TE silencing, experiences the highest percent deletions." (PMID 40789164, 2025). "Li et. al. proposed PIWIL2 as a novel prognostic marker to predict distant metastases in colon cancer patients who underwent radical colectomy given the association between PIWIL2 expression and the presence of distant metastasis, lymph node involvement, and clinical stage." (PMID 38303021, 2024). "Logistic regression analysis revealed that an increased expression of EIF2C1 and PIWIL2 was significantly associated with occurrence of colon cancer tissue compared with non-cancer tissue." (PMID 20146808, 2010). "Of the EIF2C1-4 and PIWIL1-4 analyzed by logistic regression, we observed that an increased expression of EIF2C1 and PIWIL2 was significantly associated with occurrence of colon cancer tissue compared with non-cancer tissue." (PMID 20146808, 2010). "PIWIL1 promotes cancer growth and is associated with increased mortality; increased levels of PIWIL2 have been reported in breast and cervical cancer; and increased levels of PIWIL3 and PIWIL4 have been reported in colon cancer." (PMID 26373553, 2015). "Moreover, PIWIL2 and PIWIL4 also has impacts on metastasis (particularly PIWIL2 which has a role in colon cancer)." (PMID 34193172, 2021). "Detected by using a luciferase reporter construct and western blots, piwi-like protein 2 (Piwil2) may regulate a 2-kb MMP-9 promoter fragment and apoptotic pathways in colon cancer." (PMID 24476461, 2014). "Furthermore, the knockdown of PIWIL2 in SW620 and SW480 cell lines derived from colon cancer significantly reduced invasive proliferation." (PMID 25384072, 2014).
glioma (6 papers, 2019 to 2025). A benign or malignant brain and spinal cord tumor that arises from glial cells (astrocytes, oligodendrocytes, ependymal cells). "Similarly, low expression of PIWIL2 has been linked to better patient survival in other cancers such as glioma and gastric cancer." (PMID 38303021, 2024). "In vitro knockdown of PIWIL2 in glioma cells was shown to induce cell cycle arrest and increase apoptosis, and PIWIL2 silencing suppressed the migration of glioma cells." (PMID 39849644, 2025). "There has been found to be a correlation between PIWIL2 expression, and the Ki-67 index and the grade of human glioma." (PMID 33109195, 2020). "In vitro studies showed that knock-down of PIWIL2 in glioma cells induced cell cycle arrest and promoted apoptosis." (PMID 33109195, 2020). "In vivo, PIWIL2 knockdown in glioma cells induces cell cycle arrest, increases apoptosis, and inhibits glioma cell migration." (PMID 31399034, 2019). "PiR-598, piR-8041, piR-DQ590027, piR-DQ593109, PIWIL1, PIWIL2, PIWIL3, and PIWIL4 may all be involved in the pathogenesis of glioma, and could be diagnostic markers for glioma." (PMID 33109195, 2020). "PIWIL2 is highly expressed in glioma and correlates with poor patient prognosis." (PMID 31399034, 2019). "Knockdown of PIWIL2 in glioma cells can inhibits glioma cell migration." (PMID 31727866, 2019). "PIWIL2 may therefore be a prognostic factor for survival of glioma patients." (PMID 33109195, 2020). "In addition, silencing of PIWIL2 expression inhibited the migration of glioma cells." (PMID 33109195, 2020).
lung carcinoma (6 papers, 2015 to 2025). "Another study from chronic lymphocytic leukemia and lung cancer showed that ts-3676, ts-4521, ts-46, ts-47, ts-49, ts-53, and ts-101 were down-regulated and mutated, which can form complexes by interacting with Piwi-like protein 2 (PIWIL2)." (PMID 40295511, 2025). "On the other hand, PIWIL2/HILI has emerged as a pivotal player in lung cancer, the second most prevalent cancer worldwide, according to the 2020 statistics." (PMID 39717847, 2024).
male infertility (6 papers, 2012 to 2026). The inability of the male to effect fertilization of an ovum after a specified period of unprotected intercourse. "The loss of core components (e.g., Mili/Piwil2, Miwi2/Piwil4, Mov10l1) causes TE de-repression, DNA damage, meiotic arrest, and male infertility." (PMID 41614953, 2026). "Previous studies have shown that hypermethylation of the PIWIL2 and TDRD1 promoter regions, which are involved in the PIWI-piRNA pathway, is associated with abnormal DNA methylation and male infertility in humans." (PMID 35315771, 2022). "The SCO phenotype of Mili−/− mice was similar to that of the patient included in our study, suggesting that the LoF variant in PIWIL2 affected male infertility and caused SCOS phenotype." (PMID 36153567, 2022). "Our study provided new evidence that PIWIL2 is a male infertility gene in humans." (PMID 36153567, 2022). "DNMT3L as well as PIWIL2 and TDRD1 null models revealed a loss of methylation at LINE-1 and intracisternal A-particle (IAP) transposons, leading to reactivation of repetitive elements that contribute to meiotic arrest and male infertility." (PMID 23112866, 2012). "The patient’s father and brother were heterozygous carriers, suggesting that the heterozygous frameshift variant in PIWIL2 may not affect male infertility." (PMID 36153567, 2022). "Five of these genes were characterized as male infertility‐related genes, including Polo‐like kinase 4 (PLK4), AGTPBP1, KISS1 receptor, Meiosis Expressed Gene 1 (MEIG1), and Piwi Like RNA‐Mediated Gene Silencing 2 (PIWIL2)." (PMID 37937809, 2024). "Recent studies have also suggested PIWIL2 as the candidate gene of male infertility in men, although without functional validation." (PMID 36153567, 2022).
non-small cell lung carcinoma (6 papers, 2015 to 2025). A group of at least three distinct histological types of lung cancer, including non-small cell squamous cell carcinoma, adenocarcinoma, and large cell carcinoma. "The data in non-small cell lung cancer are conflicting with one study reporting higher expression of PIWIL2 mRNA in the tumor and its association with poor survival, while another study showed a downregulation of PIWIL2 mRNA." (PMID 38303021, 2024). "It has been reported that downregulation of PIWIL1 and PIWIL2 by promoter CpG island hypermethylation has been observed in other types of tumors like testicular or non-small cell lung cancer." (PMID 32357464, 2020). "PIWIL2 protein expression has also been found to be downregulated in non-small cell lung cancer samples in comparison to the normal tissue (p < 0.001)." (PMID 31443431, 2019). "Similarly, the overexpression of PIWIL2 promoted cell proliferation, and PIWIL2 interference arrested non-small cell lung cancer cells at the G2/M stage." (PMID 39849644, 2025). "The intersection of the two was taken to screen five non-small cell lung cancer signature genes from the training sets GSE151103 and GSE33532: DOCK6, GPC2, RHEBL1, RNPC3, and PIWIL2." (PMID 36386821, 2022).
seminoma (6 papers, 2014 to 2023). A radiosensitive malignant germ cell tumor found in the testis (especially undescended), and extragonadal sites (anterior mediastinum and pineal gland). "Interestingly, the expression of the short PIWIL2 isoform was high in undifferentiated seminomas and decreased in tumours with a greater degree of differentiation." (PMID 35204687, 2022). "Moreover, expression of PIWIL1 and PIWIL2 was upregulated in seminomas, but not in non-seminoma tumours." (PMID 35204687, 2022). "Therefore, we extended our study to several TGCTs samples (4 undifferentiated seminomas, 4 differentiated nonseminomatous tumors and 2 mixed tumors) and examined them for presence of different PIWIL2 isoforms using two antibodies: specific to exons 14–16 and the full-length protein." (PMID 25384072, 2014). "Downregulation of PIWIL1, PIWIL2, PIWIL4, and TDRD1 genes expression due to hypermethylation of their promoters was also observed in primary TGCTs (both seminomas and nonseminomas) in comparison to normal testicular tissues." (PMID 35204687, 2022).
hepatocellular carcinoma (5 papers, 2010 to 2025). A malignant tumor that arises from hepatocytes. "In the hepatocellular carcinoma tissues, Piwil2 showed two expression patterns (nuclear co-expression and nuclear and cytoplasmic expression) and Piwil4 showed four patterns (nuclear co-expression, nuclear and cytoplasmic co-expression, cytoplasmic co-expression, and non-coexpression)." (PMID 27894076, 2017).
prostate carcinoma (5 papers, 2020 to 2024). A carcinoma that arises from epithelial cells of the prostate gland. "PIWIL2 has also been found to be involved in the effects of the overexpression of piR-4447944 in prostate cancer cells." (PMID 39596284, 2024). "The study demonstrated that piR-4447944 plays a critical role in promoting androgen-independent growth in prostate cancer by interacting with PIWIL2." (PMID 39596284, 2024). "For this concern, it has been reported how PIWIL2 regulates invasion abilities of prostate cancer cells through modulation of EMT protein expression." (PMID 32357464, 2020). "Knocked-down PIWIL2 decreased invasion and migration of prostate cancer-derived PC 3 cell line." (PMID 35204687, 2022).
bladder cancer (4 papers, 2010 to 2022). "The notion is also supported by the fact that Piwil2 transcripts were undetectable in the bladder cancers by real-time RT-PCR with the primers amplifying first 6 exons of PIWIL2, which are absent in PL2L genes." (PMID 20975993, 2010).
ovarian carcinoma (4 papers, 2018 to 2024). A malignant neoplasm originating from the surface ovarian epithelium. "Another study indicated that overexpression of PIWIL2 acts as an oncogene in ovarian cancer by inhibition of apoptosis and promotion of proliferation." (PMID 38896069, 2024). "PIWIL2 overexpression promotes platinum resistance in ovarian cancer cells by enhancing cisplatin‐induced DNA damage repair." (PMID 38896069, 2024). "PIWIL2, also known as cancer/testis antigen, has been found to be highly expressed in a variety of cancer types, such as prostate, colorectal, breast, cervical, gastric, and ovarian cancer." (PMID 37941038, 2023).
renal cell carcinoma (4 papers, 2019 to 2025). "Clinically, reduced expression of PIWIL4, along with PIWIL1 and PIWIL2, is correlated with unfavorable survival in renal cell carcinoma." (PMID 41208974, 2025). "Downregulation of piRNA pathway genes in cancer may be uncommon but have been reported in testicular germ cell tumor (PIWIL1, PIWIL2, PIWIL4 and DDX4) and renal cell carcinoma (PIWIL1, PIWIL2 and PIWIL4) and now, also in our expression study for PIWIL2, PIWIL4 and TDRD1." (PMID 33374923, 2020).
germ cell tumor (3 papers, 2014 to 2020). A benign or malignant, gonadal or extragonadal neoplasm that originates from germ cells. "In this work, we attempted to expand the knowledge on the presence of different PIWIL2 isoforms in various testicular cancer cell lines and testicular germ cell tumors (TGCTs), as well as elicit correlations of PIWIL2 isoforms expression with neoplastic profiles and clinical manifestations of TGCTs." (PMID 25384072, 2014).
lymph node metastasis (3 papers, 2015 to 2023). "PIWIL2 has a high expression in PCa, which positively correlates with Gleason score, lymph node metastasis, and advanced TNM stage (T3-T4)." (PMID 38031146, 2023). "Patients with high PIWIL2 have more lymph node metastasis, poor histological type, clinical stage, and shorter survival." (PMID 38031146, 2023). "The expression of Piwil1, Piwil2, Piwil13, and Piwil4 were positively correlated with T stage, lymph node metastasis and clinical TNM and patients with higher expression had shorter survival time." (PMID 26506848, 2015).
neuroblastoma (3 papers, 2010 to 2023). Neuroblastoma (NB) is the most common solid, extracranial childhood tumor. "In fact, it's an interesting phenomenon that this piRNA is up-regulated in Piwil2-iCSCs, but downregulated in neuroblastoma." (PMID 37941038, 2023).
soft tissue sarcoma (3 papers, 2012 to 2024). A malignant neoplasm arising from muscle tissue, adipose tissue, blood vessels, fibrous tissue, or other supportive tissues excluding the bones. "The only cancer type exhibiting better cancer-specific survival with higher levels of PIWIL2 mRNA is soft tissue sarcoma." (PMID 38303021, 2024). "In soft tissue sarcoma, low PIWIL2 mRNA expression correlated significantly with poor prognosis." (PMID 32987715, 2020).
Anxiety (2 papers, 2021 to 2023). Intense feelings of nervousness, tension, or panic often arise in response to interpersonal stresses. "Mili/Piwil2-knockout mice show hyperactivity and reduced anxiety-like behaviors." (PMID 37207075, 2023).
breast tumors (2 papers, 2010 to 2014). "In addition, expression of the PIWIL2 protein was also found in different tumors examined, including prostate, breast, pancreatic, gastrointestinal, ovarian and endometrial cancer of human and in breast tumors, rhabdomyosarcoma and medulloblastoma of mouse." (PMID 20146808, 2010).
cervical intraepithelial neoplasia (2 papers, 2020 to 2021). "Piwil2 reprograms HPV-infected reserve cells in the cervix into tumor-initiated cells (TICs) and upregulates Wnt3a expression sequentially, which leads to cervical intraepithelial neoplasia (CIN) and ultimately squamous cell carcinoma (SCC)." (PMID 34257574, 2021).
embryonal carcinoma (2 papers, 2018 to 2022). A non-seminomatous malignant germ cell tumor characterized by the presence of large germ cells with abundant cytoplasm resembling epithelial cells, geographic necrosis, high mitotic activity, and pseudoglandular and pseudopapillary structures formation. "The role of PIWIL4 in brain is poorly understood, despite recent reports indicating that PIWIL2 and PIWIL4 are associated with autism, and that PIWIL4 helps modulate neuronal differentiation from human embryonal carcinoma cells." (PMID 35015250, 2022).
endometrial cancer (2 papers, 2010 to 2015). Primary or metastatic malignant neoplasm involving the endometrium (mucous membrane that lines the endometrial cavity). "In this study, we confirmed that the expression of Piwi proteins (Piwil1, Piwil2, Piwil13, and Piwil4) are different in endometrial cancer cell lines and we mainly focused on the role of Piwil1 in endometrial cancer." (PMID 26506848, 2015).
leukemia (2 papers, 2010 to 2024). A malignant (clonal) hematologic disorder, involving hematopoietic stem cells and characterized by the presence of primitive or atypical myeloid or lymphoid cells in the bone marrow and the blood. "PIWIL2 silencing in precancerous stem cells from mouse dendritic cell-like leukemia led to a decrease in cell growth, while overexpression of PIWIL2 in mouse bone marrow cells increased cell proliferation." (PMID 38303021, 2024).
lung fibrosis (2 papers, 2023 to 2024). "PIWIL2 and PIWIL4 have also been implicated in the unfolded protein response in human airway epithelial cells, with PIWIL2 potentially upregulated by NF-E2-related factor 2, contributing to the attenuation of radiation-induced lung fibrosis." (PMID 39596284, 2024). "Inhibiting key purine biosynthesis enzymes, IMP dehydrogenase 1 and 2 (IMPD1 and 2), abolished the protective effect of Nrf2 signaling on lung fibrosis, demonstrating evidence of a Nrf2/PIWIL2/purine metabolism axis." (PMID 37375769, 2023). "However, a recent study demonstrated that the therapeutic effect of Nrf2 activity on the progression of murine radiation-induced lung fibrosis was controlled through the piwi-like RNA-mediated gene silencing 2 (PIWIL2)-mediated reprogramming of purine metabolism." (PMID 37375769, 2023).
melanoma (2 papers, 2010 to 2022). A malignant, usually aggressive tumor composed of atypical, neoplastic melanocytes. "MILI, also named PIWIL2 in humans, inhibited melanoma cell metastasis, probably providing a novel perspective on melanoma treatment." (PMID 35637965, 2022).